ENSG00000207027
Synonyms: LOC124900262
Gene: Small nucleolar RNA gene on chromosome 8 (23,806,229 to 23,806,377, reverse strand). Ensembl gene ENSG00000207027.
Gene Ontology:
Biological process: RNA processing
Cellular component: nucleolus
Homologues: Paralogues in human: SNORA67 (83% identical).